CYP19A1 (cytochrome P450 family 19 subfamily A member 1)
Diseases named in the same sentence as CYP19A1 in open-access papers (continued):
Sharing a sentence is not in itself a finding about the gene and the disease.
tumor (continued). "However, in agreement with our results, many studies have not shown any association between CYP19A1 gene expression and variables such as age, tobacco use, menopausal status, grade, nodal status, tumor stage, estrogen receptor, progesterone and histological type." (PMID 32460723, 2020). "Statistics of overall survival (months) of tumor samples for ERS1 gene expression, ERS2 gene expression, CYP19A1 gene expression and aromatase protein concentration (ARO) for each combination of low and high expression groups (lower and higher than median)." (PMID 25310221, 2014). "We found that high CYP19A1 expression levels in primary tumours were significantly correlated with a higher TNM stage and T/N stage, suggesting that CYP19A1 might play an indispensable role in NSCLC metastasis." (PMID 38238831, 2024). "Patients with high risk factors, such as early onset of menstruation, null parity, and age >50 years, displayed low levels of CYP19A1 gene expression in tumor and peritumoral tissue, unlike the findings of Clemons and Goss." (PMID 34133482, 2021). "Conversely, E-cadherin-negative tumor cell lines with a fibroblastoid morphology expressed CYP19A1 at roughly the same level as untransformed cell lines." (PMID 29363090, 2018). "Mice after androstenedione (known substrate of CYP19A1) treatment were presenting more advanced tumor development in comparison to the mice which did not receive the compound." (PMID 27783191, 2017). "However, bubble charts which illustrated gene clustering in the model highlighted that only CYP19A1 exhibited high expression in various tumor clusters but not in normal gastric tissues." (PMID 41050076, 2025). "Furthermore, the sponging of the CYP19A1 mRNA by MIR98 contributed to estrogen depletion and decreased tumor cell proliferation, migration, invasion, and angiogenesis, suggesting application of MIR98 as a therapeutic and diagnostic molecule in clinical settings." (PMID 33920789, 2021). "Results of these studies above as well as those from our present investigation all indicated that the tumor cells in both HCC and MLC may secrete potent inducers of CYP19A1 into adjacent microenvironment of the human liver, which resulted in an induction of intrahepatic aromatase in hepatocytes." (PMID 23930207, 2013). "In contrast, a significant negative correlation of CYP19A1 and ESR1 levels was found in tumor cell lines (r = −0.639, P = 0.012)." (PMID 29363090, 2018). "Tumor and non-tumor lung tissue samples were analyzed for the mRNA expression of ERS1, ERS2 and CYP19A1 by RT-PCR." (PMID 25310221, 2014). "Although their exact mechanism of action in controlling tumor growth is not known, EDCs may inhibit steroidogenic enzymes such as CYP17A1 or CYP19A1 which are involved in the production of androgens or estrogens." (PMID 38397440, 2024).
cancer (62 papers, 2002 to 2025). A tumor composed of atypical neoplastic, often pleomorphic cells that invade other tissues. "Our research showed that CYP19A1-rs28757157 was associated with increased cancer risk in the population aged under 60 years, females, smokers, and drinkers." (PMID 36527059, 2022). "Studies have identified SNPs in CYP19A1 that are associated with cancer risk primarily in European Americans (EA), North Indian and Chinese populations." (PMID 25647083, 2015). "CYP19A1 is critical for estrogen biosynthesis, thus, identifying genetic variants in CYP19A1 is necessary for assessing cancer risk and predicting response to aromatase inhibitor drugs across ethnically diverse and disparate populations." (PMID 25647083, 2015). "CYP19A1 genetic variation related studies investigated the association with various hormone related cancers such as breast, endometrial, ovarian, and prostate." (PMID 23110082, 2012). "Our findings of the potential association between CYP19A1 including the rs749292 variant and HGF levels suggest that CYP19A1 is also likely associated with cancer progression due to elevated HGF levels." (PMID 22848710, 2012). "Many studies examined CYP19A1 with hormonally associated cancers, such as breast, prostate, endometrial." (PMID 23110082, 2012). "SNPs in CYP19A1 were found to be associated with cancer risk." (PMID 36527059, 2022). "While much progress has been made describing the active promoters in cancer, many unknowns remain regarding the factors that promote aberrant CYP19A1, especially for transcription associated with the more distal alternative exons such as I.1." (PMID 30479694, 2018). "Finally, by determining the association of rs10046 genotypes with CYP19A1 expression, we addressed a proposed mechanism by which genetic variants in CYP19A1 might affect circulating estrogen levels and (breast) cancer risk." (PMID 29363090, 2018). "For this study, we focused on CYP19A1 SNPs that were predicted to localize within regulatory binding regions, and/or predicted to associate with regulatory proteins involved in pre-mRNA processing, mRNA metabolism and transport, and previously associated with cancer risk and patient outcomes." (PMID 25647083, 2015). "The differential expression of PIK3R1, AKR1C3, EGFR, ESR1, PIK3CD, CYP3A4, and CYP19A1 across various cancer types and stages illuminates their potential as biomarkers for cancer progression and prognosis." (PMID 39204124, 2024). "On the other hand, previous studies have described that some of the multiple mechanism through which AM decreases cancer cell proliferation involve the reduction in ER expression and the inhibition of CYP19A1 activity and ER antagonism." (PMID 38004441, 2023). "Despite various cancer subtypes, malignant breast tissues express high levels of aromatase (CYP19A1), along with large amounts of estrogens, particularly E2, which are synthesized from androgens by the aromatase enzyme." (PMID 36614200, 2023). "Recent studies have revealed that CYP19A1 gene plays a crucial role in cancer initiation and development." (PMID 36527059, 2022). "In the group with relapsed cancer, CYP19A1 gene expression was significantly higher in women with a hybrid luminal molecular subtype than in women with a triple-negative subtype." (PMID 32460723, 2020). "Up- and down-regulation of candidate in cancer tissues was still statistically significant different in cancer tissues for the selected CYP450s, except for CYP19A1." (PMID 31258835, 2019). "The algorithmic analysis and cancer driver analysis on steroidogenic lipidomes found that CYP19A1 is considered a landmark enzyme affecting disease prognosis, and is considered a valuable target for therapy." (PMID 27893427, 2017). "Therefore, inhibition of CYP19A1 has become an established therapeutic strategy for these types of cancers." (PMID 40807256, 2025). "Besides, recent research has also shown that CYP19A1 can regulate ER stress to affect different cancer development." (PMID 41050076, 2025).
cancer (continued). "DIM inhibits aromatase/cytochrome P45019A1 (CYP19A1) activity, which may contribute to its anti-cancer effects in estrogen-dependent breast cancers." (PMID 37834026, 2023). "CYP17A1, as well as CYP19A1, is targeted by inhibitors in cancer treatments." (PMID 36557005, 2022). "Interestingly, the reduction of AKT activation induced by the combination of COX-2 and CYP19A1 inhibitors in MPM cells represents a critical pathway in the response to treatment as detected in the onset of drug resistance in a variety of cancers." (PMID 34404424, 2021). "A series of genes (e.g. CYP1A2, CYP3A4, CYP19A1), related to cancer in Cytochrome P450 Family, were down-regulated, with the exception of CYP2E1, which was up-regulated and may be involved in carcinogenic process of cervical cancer." (PMID 28225065, 2017). "Thus, investigations into whether CYP19A1 intron SNPs contribute to variations in cancer incidence, outcomes and pharmacological response seen in populations of different ancestry may prove beneficial." (PMID 25647083, 2015). "Additionally, the CYP19A1 gene may be relevant to cancer progression, given its potential role in regulating HGF which has angiogenic and mitogenic properties." (PMID 22848710, 2012). "Among these shared targets, several key genes involved in cancer-related pathways were identified, including EGFR, PARP1, SRC, MET, GSK3B, and CYP19A1." (PMID 40963691, 2025). "Topological analysis of the PPI network, using the STRING database and Cytoscape 3.10.2, identified seven core targets crucial in cancer pathways: CYP3A4, PIK3R1, PIK3CD, ESR1, AKR1C3, EGFR, and CYP19A1." (PMID 39204124, 2024). "These qPCR results confirmed a similar distribution of gene expression; overexpression of CYP1B1, CYP7A1, CYP17A1, and CYP19A1, and repression of CYP1A2, CYP2B6, CYP2C19, and CYP26A1 was observed in cancer tissues." (PMID 31258835, 2019). "Since many anti-cancer drugs target enzymes from the steroidogenic pathway, we tested the effect of curcuminoids on cytochrome P450 CYP17A1, CYP21A2, and CYP19A1 enzyme activities." (PMID 31533365, 2019). "Not only do DVLs bind to multiple tissue-specific aromatase promoters that are aberrantly activated in cancer, but the role of DVL-1 vs. DVL-3 appears to play a promoter-specific and cell- type dependent role that can lead to either activation or repression of CYP19A1 transcripts." (PMID 30479694, 2018).
infection (12 papers, 2014 to 2025). The state of being infected such as from the introduction of a foreign agent such as serum, vaccine, antigenic substance or organism. "The immunofluorescence performed the vector infection and qRT-PCR showed increased or decreased levels of CYP19A1 expression, indicating the validity of this viral system." (PMID 32990306, 2020). "Thereafter, the expression of HSD3B increased, accompanied by increased CYP19A1 mRNA expression and E2 production in B.suis.S2-infected cells at 48 h post-infection." (PMID 26904517, 2016). "The expression of CYP19A1 mRNA decreased at 12 h post-infection and increased after 24 h post-infection in B.suis.S2-infected GTCs." (PMID 26904517, 2016). "Interestingly, we found that the regulation of CYP11A1 by CYP19A1 was utterly disrupted in the presence of H. pyloriWT infection, with CYP11A1 remaining at a high level without the impact of CYP19A1 in response to H. pyloriWT infection." (PMID 39113698, 2024). "In contrast, H. pyloriWT infection partly disrupted the negative impact of CYP11A1 on CYP19A1: CYP11A1 knockdown could still upregulate CYP19A1; CYP11A1 by PCR overexpression could not downregulate CYP19A1 and WB." (PMID 39113698, 2024). "In addition, H. pyloriWT infection totally disrupted the negative impact of CYP19A1 on CYP11A1: CYP11A1 was immune from the influence of CYP19A1 and could maintain a high expression level in GC cells infected with H. pyloriWT." (PMID 39113698, 2024). "Furthermore, CYP11A1-overexpression could no longer decrease CYP19A1 once infected by H. pyloriWT, while CYP11A1-knockdown could still up-regulate CYP19A1 in GC cell with H. pyloriWT infection, indicating H. pyloriWT may exert an indirect impact on CYP19A1 expression via CYP11A1." (PMID 39113698, 2024).
cardiovascular disease (4 papers, 2010 to 2023). "This study is the first demonstrating a significant polymorphism interaction of CYP19A1 gene with gender on the outcome of cardiovascular disease." (PMID 25861479, 2015). "A recent study examined genetic variants of CYP19A1 gene for their role in the differences depending on gender with regard to the outcome of cardiovascular disease." (PMID 25861479, 2015). "Given the postulated role of estrogens and androgens on cardiovascular health and sex-related differences in cardiovascular disease risk factors, we hypothesized that CYP19A1 polymorphisms would be associated with outcomes in cardiovascular disease." (PMID 21170323, 2010). "A recent study examined genetic changes of CYP19A1 gene to relate them to the differences according to gender in the outcome of cardiovascular disease." (PMID 25861479, 2015). "We sought to examine genetic variation in CYP19A1 for its potential role in sex differences in cardiovascular disease outcomes." (PMID 21170323, 2010).
metabolic disease (4 papers, 2013 to 2024). A congenital disorder (due to inherited enzyme abnormality) or acquired (due to failure of a metabolically important organ) disorder resulting from an abnormal metabolic process. "Novel compounds that are safe and non-toxic are needed to target CYP17A1 and CYP19A1 activities to treat metabolic disorders resulting from excess production of androgens or estrogens." (PMID 31533365, 2019).
adenocarcinoma (2 papers, 2022 to 2023). A common cancer characterized by the presence of malignant glandular cells. "The authors suggested that CYP19A1 polymorphisms may lead to elevated levels of local estrogen surrounding the lungs, and this excess local estrogen production may be one of the factors associated with the polycentric development of adenocarcinoma." (PMID 36527059, 2022).
nervous system disease (2 papers, 2022 to 2023). "One disease also matches different targets; for example, nervous system disease can involve CYP19A1, TRPM8, CHRM2, etc." (PMID 37701374, 2023).
retinopathy (1 paper, 2020). "Furthermore, on the basis of stratification analysis results, haplotype Crs1062033Grs17601876Ars3751599 in CYP19A1 was found to be associated with the decreased risk of retinopathy in T2DM patients." (PMID 32814585, 2020).
CYP19A1 also shares sentences with these, for which no sentence is quoted: Type 2 Diabetes (5 papers); adenomyosis (4); papilloma (4); Alzheimer disease (3); dementia (3); depression (3); metabolic syndrome (3); Oral Cancer (3); Adrenal Hyperplasia (2); Azoospermia (2); brain ischemia (2); breast adenocarcinoma (2); Cerebral ischemia (2); cognitive deficits (2); granulosa cell tumor (2); Hyperinsulinemia (2); hyperlipidemia (2); lung disease (2); acute coronary syndrome (1); acute myeloid leukemia (1); Alcohol (1); alopecia (1); ameloblastoma (1); atherosclerosis (1); bacterial infection (1); Bardet-Biedl syndrome (1); cancers of the oral cavity (1); Chagas disease (1); chondroblastoma (1); co-infections (1).
A further 47 diseases each share a sentence with CYP19A1 in 1 paper.